PDIA3 (protein disulfide isomerase family A member 3)
Diseases named in the same sentence as PDIA3 in open-access papers (continued):
Sharing a sentence is not in itself a finding about the gene and the disease.
cancer (continued). "Our results indicate that PDIA3 might affect the development, prognosis, and therapy of cancers by associating with immune cells." (PMID 35401558, 2022). "The lectin chaperones calreticulin (CALR) and calnexin (CANX), together with their co-chaperone PDIA3, are increasingly implicated in studies of human cancers in roles that extend beyond their primary function as quality control facilitators of protein folding within the endoplasmic reticulum (ER)." (PMID 35860021, 2022). "In conclusion, the results of this study suggest that PDIA3 may affect the occurrence, prognosis, and treatment of a variety of cancers through its association with 11 immune cells, such as B-cell memory, plasma cells, and T-cell CD4 naive." (PMID 36046686, 2022). "Besides, oxidative phosphorylation, unfolded protein response, MYC targets, and MTORC1 signaling were also tightly associated with PDIA3 expressions in cancers." (PMID 35401558, 2022). "Then, we assessed the association between PDIA3 and prognosis of cancer patients." (PMID 35401558, 2022). "And PDIA3 is frequently overexpressed in various tumors, serving as a potent pan-cancer prognostic biomarker." (PMID 40948653, 2025). "PDIA3 has pleiotropic functions, proven to promote the proliferation and invasion of cancer cells, and can directly participate in the replication of the influenza virus." (PMID 40996975, 2025). "The downregulation of PDIA3 results in apoptosis triggering in several cell lines and is reported to be overexpressed in several cancer types, making it a potential biomarker and drug target." (PMID 40827917, 2025). "Wound-healing and Transwell assays provided evidence of PDIA3’s impact on cancer cell migration, with the introduction of PD-1 antibodies reversing the enhanced migratory effects observed in PDIA3-overexpressing cells." (PMID 38761176, 2024). "In contrast, PDIA3, which participates in cancer initiation, progression, and chemosensitivity, has recently been proposed as a novel therapeutic target for GBM therapy." (PMID 38607010, 2024). "Use of more sophisticated systems, such as tumor spheroids in vitro or mouse genetic models of cancer, would give a clearer view on, for example, the relative effects of PDIA3 inhibition on primary or metastatic tumors or effects on the ECM and TME over time." (PMID 36912485, 2023). "It has been reported that PDIA3 participates in cancer initiation, progression and chemosensitivity, and its inhibition has been shown to decrease cell proliferation in several cancers." (PMID 37686085, 2023). "It was postulated that PDIA3 can be treated as a chemoprevention target and prognostic marker in cancer patients." (PMID 37960182, 2023). "Consistent with our finding, individual cancer-specific EMT signature genes such as PDIA3, HLA-A, BCAM, B2M, LGALS3BP, and HLA-C were highly expressed in cancer cells from infiltrated and excluded TMEs." (PMID 38086828, 2023). "Recent studies have shown that PDIA3 is upregulated in various cancers, including breast, prostate, ovarian, glial cell carcinoma, and cervical adenocarcinoma, and is involved in their development, progression, and response to chemotherapy." (PMID 37909009, 2023). "GSEA analysis showed that PDIA3 and its related differential genes are involved in a variety of important biological functions closely related to cancer and affect OSCC through the Hedgehog, TGF-β, Wnt-β catenin, and KRAS signaling pathways." (PMID 38213579, 2023). "Further studies are needed to investigate the molecular mechanisms underlying the oncogenic role of PDIA3 in OSCC and other types of cancer." (PMID 38213579, 2023). "Gene set enrichment analysis (GSEA) indicated that PDIA3 is involved in various important biological functions and signaling pathways closely related to cancer development." (PMID 38213579, 2023). "Given its role in cancer, PDIA3 has emerged as a potential biomarker and therapeutic target for cancer treatment." (PMID 38213579, 2023).
cancer (continued). "PDIA3 is also overexpressed in colon and breast cancers and is involved in the formation and development of these two types of cancers." (PMID 38213579, 2023). "The silencing of PDIA3 and 1,25(OH)2D3 treatment reversed the expression of those cancer-related genes in A431 cells." (PMID 38201216, 2023). "The overexpression of PDIA3 is common in many types of cancers, and its inhibition offers a valid alternative for new treatments." (PMID 37686085, 2023). "Functional enrichment analysis indicated that PDIA3 is involved in multiple cancer-related cellular functions and signaling pathways." (PMID 38213579, 2023). "NRP1 was closely associated with a variety of genes in pan-cancer studies, such as IGF-1, PDIA3, and CD36." (PMID 37450415, 2023). "PDIA3, a multifunctional member of the PDI family with multiple cellular functions, has been linked to various types of cancers, neurological disorders and other diseases." (PMID 37686085, 2023). "In conclusion, the pan-cancer analysis of PDIA3 in this study shows the correlation between the differences of PDIA3 in tumor tissues and normal tissues and clinicopathological features." (PMID 36046686, 2022). "To firstly comprehend the basic information of PDIA3 in cancer, we employed the TCGA and GTEx databases to evaluate the expression level of PDIA3 in cancers compared with normal tissues." (PMID 35401558, 2022). "Based on the data downloaded from the TCGA database, the expression levels of PDIA3 in tumor tissues and matched normal tissues of 33 kinds of cancers were analyzed." (PMID 36046686, 2022). "To understand the main cell types that express the PDIA3 in cancer microenvironments, we performed the single-cell analysis of PDIA3 in 79 single-cell datasets of cancer samples." (PMID 35401558, 2022). "To illustrate the relationships between PDIA3 and cancer immunity, we further excavate the correlations between PDIA3 expression and immune cell infiltrations." (PMID 35401558, 2022). "The expression of PDIA3 is increased in nearly 70% of cancers, with the highest expression in liver, lung, placenta, pancreas, and kidney and the lowest expression in heart, skeletal muscle, and brain." (PMID 36046686, 2022). "The outcomes revealed a clear increase of the PDIA3 expression in most cancer types, except KIRP, LAML, and READ." (PMID 35401558, 2022). "The differential expression genes (DEGs) between low- and high-PDIA3 subgroups in each cancer were used to perform GSEA in order to discern the PDIA3-associated cancer hallmarks." (PMID 35401558, 2022). "Among refluxed ER proteins, the cytosolic fraction of ERp57/PDIA3 in cancer cells is enriched up to ∼ 70% compared with only ∼ 10% enrichment in non-cancer control cells." (PMID 35109791, 2022). "For example, these processes were mostly significantly enriched in high-PDIA3 cancer subgroups, but reversed results were found in CHOL, LUAD, PRAD, PAAD, and THCA." (PMID 35401558, 2022). "PDIA3 is overexpressed in most cancer types and exhibits prognosis predictive ability in various cancers, and it is especially expressed in the malignant cells and monocytes/macrophages." (PMID 35401558, 2022). "Another essential discovery of our study is that the expression of PDIA3 is highly related to immune infiltration in pan-cancer." (PMID 35401558, 2022). "The relative expression level of PDIA3 in 24 different tumor cell lines was analyzed based on the data downloaded from the CCLE database of cancer cell encyclopedia, and the expression level of PDIA3 in most normal cell lines was higher (P < 0.001)." (PMID 36046686, 2022). "The univariate Cox regression and the Kaplan–Meier method were utilized to appraise the prognostic role of PDIA3 in pan-cancer." (PMID 35401558, 2022). "It was found that there were significant differences in PDIA3 expression between tumor tissues and normal tissues among 20 types of cancers." (PMID 36046686, 2022).
cancer (continued). "In view of the results above, we subsequently analyze the predictive role of PDIA3 in ICI cancer cohorts." (PMID 35401558, 2022). "But the role of PDIA3 in cancer immune infiltrations and immunotherapy response prediction is not clear, and no comprehensive pan-cancer study has been conducted yet." (PMID 35401558, 2022). "Our results suggested that PDIA3 has the potential to predict the efficiency of ICIs in the corresponding cancers." (PMID 35401558, 2022). "Cell-surface PDIA3 has also been shown to act with glycosylated calnexin to reduce extracellular disulfide bonds and make ECM more susceptible to degradation by cancer cells." (PMID 35196163, 2022). "A recent review summarized the current knowledge on ERp57/PDIA3 in cancer and the mechanisms by which this protein is involved, starting from carcinogenesis and extending to its potentialities as a therapeutic target." (PMID 35109791, 2022). "Various studies conducted on cancer cells have shown ERp57/PDIA3 involvement in signal transduction of STAT3." (PMID 35109791, 2022). "In conclusion, a comprehensive pan-cancer analysis of PDIA3 was conducted, indicating its potential function as a prognostic biomarker for cancers and its potential function of effectively predicting immunotherapy response." (PMID 35401558, 2022). "To investigate the expression levels of PDIA3 among different tissues and cancer cell lines, we compared the PDIA3 expression levels among 31 human normal tissues and 21 cancer cell lines using the data downloaded from the GTEx and CCLE datasets." (PMID 35401558, 2022). "The Cbioportal dataset was used to explore the genomic alteration information of PDIA3 in pan-cancer." (PMID 35401558, 2022). "TIMER2.0 was the main platform to investigate the immune cell infiltrations related to PDIA3 in pan-cancer." (PMID 35401558, 2022). "The role of ERp57/PDIA3 in cancer was shown years ago, and its involvement in cancer progression suggests a potential use of ERp57/PDIA3 both as a marker and a therapeutic target." (PMID 35109791, 2022). "We appraised the aberrant expression levels of PDIA3 in pan-cancer-compared human normal tissues and further examined the upregulated PDIA3 protein expression in clinical GBM samples." (PMID 35401558, 2022). "In this study, HM450 methylation data in UCSC Xena database were used to analyze the correlation between PDIA3 expression and gene promoter methylation in 33 cancers." (PMID 36046686, 2022). "The results showed that PDIA3 was highly expressed in 19 types of cancers, but downregulated only in THCA." (PMID 36046686, 2022). "Comparison of HP and PDIA3 levels in “cancer group”, “polyp group” and “group of healthy volunteers” (x ± s)." (PMID 35860021, 2022). "In this study, we discovered that PDIA3 is a robust prognostic biomarker for pan-cancer, and it can predict the immunotherapy response effectively." (PMID 35401558, 2022). "There is a significant positive correlation between PDIA3 gene expression and microsatellite instability in 6 cancers, including COAD, HNSC, KIRC, LUSC, READ, and STAD, and the correlation coefficient with READ is the highest (cor = 0.342)." (PMID 36046686, 2022). "The role of PDIA3 in cancer regulation remains controversial since some studies suggest that it is responsible for the activation of proapoptotic pathways whereas others suggest association with cancer proliferation, inhibition of apoptosis and poor prognosis." (PMID 33761087, 2021). "The role of PDIA3 in cancer treatment remains controversial and implication of different PDIA3 transcript isoforms has not yet been studied in connection with progression of PCa." (PMID 33761087, 2021). "Previous studies pinpoint PDIA3 as a plausible candidate for studying cancer prognosis as a target for cancer treatment." (PMID 33761087, 2021).
cancer (continued). "In the present study, a novel PDIA3 transcript isoform was detected in prostate cell lines, in line with previous studies on kidney and colon cells where PDIA3N is associated with cancer progression." (PMID 33761087, 2021). "Aberrant expression of PDIA3 is shown to be correlated with poor prognosis in several cancer types and increased cell proliferation mediated by 1,25(OH)2D3 and subsequent activation of the epidermal growth factor receptor (EGFR)." (PMID 33761087, 2021). "As shown in the qRT-PCR and western blotting results, miR-587 partially reversed the cancer-promoting functions of PDIA3." (PMID 34950658, 2021). "In fact, different alterations in the regulatory pathways that modulate PDIA3 activity/expression have been reported in multiple pathologies, including neurodegenerative diseases and cancer." (PMID 33153019, 2020). "With the increasing attraction of PDIA3 in diverse cancers and immunotherapy, it is deemed as a potential molecule improving current therapeutic strategies." (PMID 32687065, 2020). "The pharmacological inhibitors tested both act to inhibit PDIA3, and a potential PDIA3-dependent function in extracellular interactions between fibroblasts and cancer cells was investigated using CM from WT or Pdia3−/− MEF." (PMID 33095243, 2020). "Some key molecules, such as CALR, HLA-A, HLA-DRB1, PDIA3, HLA-DQB1, HLA-E, and TAP2, have been implicated in various types of cancers and emphasized their important values related to the tumor progression." (PMID 31258820, 2019). "On the other hand, reduced PDIA3 expression has been reported to increase the apoptotic response to fenretinide in cancer cells, and to attenuate the IAV burden while reducing subsequent caspase-12 activation and apoptosis in epithelial cells." (PMID 29492200, 2018). "Regarding cancer progression, PDIA3 and PDIA6 gene expression are established markers of aggressiveness in primary ductal breast cancer." (PMID 29262583, 2017). "Given the involvement of PDIA3 in the cellular response to stress as well as in cancer and neurodegeneration, we felt it is useful to undertake a screening study for assessing the interaction and impact on PDIA3 protein activity of several types of flavonoids." (PMID 28044092, 2016). "Other candidate antigens included PDIA3 and hnRNP L. The metabolic requirements of cancer cells differ from that of their normal counterparts." (PMID 26581192, 2015). "In cancer related research, PDIA3 was found up-regulated in breast cancer tumor tissues compared with normal tissues recently." (PMID 24763314, 2014). "It should be noted that in some cancer types, down-regulation of PDIA3 is related to tumor progression." (PMID 23782473, 2013). "Moreover, PDIA3 has functions such as regulating inflammation and oxidative stress and inhibiting cancer cells." (PMID 40028181, 2025). "While this may help cancer cells adapt to metabolic and proteotoxic stress, aberrant PDIA3 expression can impair antigen presentation, thereby weakening anti-tumor immune responses." (PMID 41150760, 2025). "Although some PDIs (i.e., PDIA1) are expressed at high levels in normal cells, to maintain the proper protein folding and/or in response to UPR signaling, several studies have highlighted that PDIA1 and PDIA3 expression is upregulated in various cancers and neurodegenerative diseases." (PMID 39408858, 2024). "Furthermore, several studies have highlighted the significant role of PDIA3 in anti-cancer immune responses." (PMID 38213579, 2023). "Thus, in establishing the mechanism of action of PDIA3 inhibitors in cancer cells, the possible localization of PDIA3 to different cell compartments or redox environments would need to be considered." (PMID 36912485, 2023). "Continued research in this area may reveal their therapeutic potential, particularly KDELC2, TNFRSF10B, CPNE1, and PDIA3, paving the way for more effective cancer treatments." (PMID 37735436, 2023).
cancer (continued). "PDIA3 is also related to the development of drug and radiation resistance in cancers." (PMID 38213579, 2023). "PDIA3's impact on immune cell infiltration in cancer is complex and context-dependent." (PMID 38213579, 2023). "PDIA3 is a protein necessary to maintain normal cellular physiology, and its dysfunction may lead to numerous diseases, including cancers, neurodegenerative diseases, or respiratory pathologies." (PMID 38201216, 2023). "This study reveals the expression and role of PDIA3 gene as a biomarker for immunotherapy and prognosis in various cancers with the view to strengthen researchers' understanding of PDIA3 and provide new ideas and directions for PDIA3 to become a new clinical biomarker." (PMID 36046686, 2022). "PDIA3 is associated positively with the degree of infiltration of CD4+ T cells, CAF, MDSC, neutrophils, and macrophages in most cancers, indicating that PDIA3 is most likely to affect the development and prognosis of cancers by shaping the tumor microenvironment." (PMID 35401558, 2022). "In addition, PDIA3 is the pan-cancer gene and a factor independently predicting prognosis in the prognostic outcome of KIRP and KICH cases; meanwhile, it significantly affects immunotherapeutic response among THYM, LGG, and READ cases." (PMID 36457341, 2022). "In conclusion, PDIA1 and PDIA3 represent the most abundant isoforms in multiple cancer cell lines and are also bound to membranes and released extracellularly providing the rationale of the development of anti-PDIA1 and anti-PDIA3 therapy targeted to extracellular PDIs." (PMID 35725466, 2022). "Firstly, we assessed the expression level of PDIA3 in pan-cancer based on TCGA and GTEx data." (PMID 35401558, 2022). "PDIA3 affects the occurrence and development of a variety of cancer tissues and regulates the proliferation of cancer cells, playing a vital role in the prognosis and treatment of malignant tumors." (PMID 36406049, 2022). "Two of the most studied molecules are CALR and PDIA3, starting from their relation with cancer." (PMID 36213269, 2022). "A high expression of PDIA3 correlates with prognosis, immune regulators, immune cell infiltration, tumor microenvironment, TMB, and MSI in various cancers; hence, we believe that PDIA3 blocking may be an efficient and feasible therapy for cancers." (PMID 35401558, 2022). "Besides, the correlation analysis of PDIA3 and immune regulators in pan-cancer suggested that PDIA3 expression is correlated with many immune regulator gene expressions, especially in ACC, LGG, and UVM." (PMID 35401558, 2022). "Third, previous studies found that PDIA3 could mediate the induction of T cell tolerance, the differentiation of regulatory T cell, and the activation of macrophage/microglia in cancers." (PMID 36003400, 2022). "We also conducted a clinical sample test with GBM samples, and western blot analysis suggested that the expression of PDIA3 in nine GBM tissues was remarkably higher than that in normal tissues adjacent to cancer, further validating the high protein expression of PDIA3 in GBM." (PMID 35401558, 2022). "Moreover, PDIA3 features the ability to promote the proliferation of cancer cells and playing a part in cancer progression." (PMID 35860021, 2022). "How to target the PDIA3 is a constructive topic for cancer therapy." (PMID 35401558, 2022). "Therefore, in this study, the differential expression of PDIA3 in 33 kinds of tumors was analyzed to explore its ability to regulate tumor immunity as a biomarker and evaluate its role in different cancer onset stages or clinical prognosis." (PMID 36046686, 2022). "Besides, specific inhibitors that correlated with PDIA3 expression in different cancer types were also screened by using Connectivity Map (CMap)." (PMID 35401558, 2022).